STAT5B (signal transducer and activator of transcription 5B)
Diseases named in the same sentence as STAT5B in open-access papers (continued):
Sharing a sentence is not in itself a finding about the gene and the disease.
acute promyelocytic leukemia (6 papers, 2019 to 2024). An aggressive form of acute myeloid leukemia (AML), characterized by arrest of leukocyte differentiation at the promyelocyte stage, due to a specific chromosomal translocation t(15;17) in myeloid cells. "However, this mutation was identified in a chimeric protein of STAT5B and retinoic acid receptor-α (STAT5B-RARα), which is associated with acute promyelocytic leukemia (APL) and is also resistant to all-trans retinoic acid therapy." (PMID 31717342, 2019). "So far, STAT5B mutations are rare and tend only to be found in human myeloid leukemia such as CD4+ T-cell prominent granular lymphocytic (T-LGL) leukemia, chronic natural killer lymphoproliferative disorders (CLPD-NK), Acute promyelocytic leukemia (APL)." (PMID 36524006, 2022). "In acute promyelocytic leukemia (APL), some rare RARA gene rearrangements exhibit resistance to ATRA and arsenic trioxide (ATO), including ZBTB16- RARA and STAT5B- RARA41." (PMID 38902322, 2024). "Lastly, we should also mention the identification of a fusion between STAT5B and Retinoic Acid Receptor (RAR)α resulting from an interstitial deletion on chromosome 17 in acute promyelocytic leukemia (APL)." (PMID 31963765, 2020).
gastric cancer (6 papers, 2014 to 2022). A primary or metastatic malignant neoplasm involving the stomach. "The significant association of STAT5B protein expression with TNM stage was found in colorectal cancer, but not in gastric cancer." (PMID 25137041, 2014).
growth failure (6 papers, 2017 to 2021). "STAT5B deficiency gives rise to another form of PIRDs, typically associated with severe growth failure, highlighting its crucial role in the signaling pathways of IL-2, IL-15, and GH, as well as of other cytokines and growth factors." (PMID 34277517, 2021). "One destabilizing mutation has been observed in the pY pocket of STAT5B at the βC4 position (Ala630Pro) which disrupts the β-sheet, reducing protein solubility and leading to misfolding and a clinical presentation of severe growth deficiency." (PMID 31717342, 2019). "Since inactivating mutations in the human STAT5B gene have been characterized that are associated with growth failure and IGF1 deficiency and genetic loss of Stat5b leads to growth deficiency in mice, it seems likely that this molecular pathway has been conserved between rodents and humans." (PMID 29240807, 2017). "Although these growth deficiencies are likely multifactorial in etiology, the growth hormone (GH)-growth hormone receptor (GHR) interactions that recruit JAK kinase and stimulate phosphorylation of STAT5B remain intact, suggesting a breakdown in corresponding STAT5B activity." (PMID 31717342, 2019).
hepatocellular carcinoma (6 papers, 2016 to 2023). A malignant tumor that arises from hepatocytes. "Because EMT plays such a significant role in the development of aggressive hepatocellular carcinoma (HCC), studies have been conducted linking STAT5b to the invasive properties of HCC." (PMID 36755813, 2022). "Like STAT3, experimental evidence implicates STAT5B as a driver of tumorigenesis, as it can drive EMT and increased invasiveness in hepatocellular carcinoma (HCC)." (PMID 31684144, 2019).
melanoma (6 papers, 2019 to 2023). A malignant, usually aggressive tumor composed of atypical, neoplastic melanocytes. "The high expression of IRF1, JAK2, CD8A, STAT5B, and SELL was connected with a low risk of death and was a protective factor of melanoma." (PMID 32316408, 2020). "Knockdown of STAT5B in these cells causes downregulation of BCL2, which triggers cell death and G1 arrest, thus underscoring that STAT5B acts as a survival factor in melanoma." (PMID 31569642, 2019). "Moreover, the results of survival analysis indicated that the high expression of six hub genes except STAT5B was connected with improved outcomes in melanoma." (PMID 32316408, 2020). "OSM is a cytokine belonging to the IL-6 family, and in the A375 human melanoma cell line, OSM receptor signaling is mediated by JAK1, JAK2, and tyrosine kinase 2 signaling via STAT3 and STAT5b." (PMID 34067095, 2021). "In conclusion, six hub genes (IRF1, JAK2, CD8A, IRF8, STAT5B, and SELL) were discovered to distinguish the response of melanoma patients under anti-PD-1 immunotherapy via WGCNA and integrated bioinformatics." (PMID 32316408, 2020). "Taken together, IRF1, JAK2, CD8A, IRF8, STAT5B, and SELL may serve as predictive therapeutic biomarkers for melanoma and could facilitate future anti-PD-1 therapy." (PMID 32316408, 2020). "Finally, the results suggested that the expression of six genes including IRF1, JAK2, CD8A, IRF8, STAT5B, and SELL had a significant ability to distinguish the responders from non-responders to anti-PD-1 therapy in melanoma with AUC > 0.6 and pAUC > 0.7." (PMID 32316408, 2020).
anaplastic large cell lymphoma (5 papers, 2019 to 2024). Anaplastic large cell lymphoma (ALCL) is a rare and aggressive peripheral T-cell non-Hodgkin lymphoma, belonging to the group of CD30-positive lymphoproliferative disorders, which affects lymph nodes and extranodal sites. "Abnormalities affecting more downstream signaling pathways are prominent in certain PTCLs, such as JAK/STAT3 signaling in anaplastic large cell lymphoma (ALCL) and STAT5B mutations in monomorphic epitheliotropic intestinal T-cell lymphoma (MEITL) and hepatosplenic T-cell lymphoma (HSTCL)." (PMID 35954378, 2022). "Furthermore, STAT5 activation is targetable in cutaneous T cell lymphomas, bearing STAT5A and STAT5B copy number gains, and PDGFRβ-driven anaplastic large cell lymphoma." (PMID 38618957, 2024). "The oncogenic fusion protein of anaplastic lymphoma kinase (ALK) with nucleophosmin 1 (NPM1) in anaplastic large cell lymphoma leads to the activation of multiple intracellular signal transduction pathways including PI3K–AKT, MAPK/ERK, mTOR, STAT3, and STAT5B." (PMID 31690038, 2019). "This contrasts with other hematological malignancies, such as peripheral T-cell lymphomas, particularly the anaplastic large cell lymphoma (ALCL) form of the disease, where GOF mutations in STAT3, but not in STAT5B, have been observed." (PMID 38254802, 2024).
colitis (5 papers, 2015 to 2022). Inflammation of the colon. "STAT5B-deficient mice are particularly susceptible to chemically induced colitis, a fact that was attributed to apoptosis of epithelial cells and damage of the mucosal barrier." (PMID 31569642, 2019). "This is consistent with an increased susceptibility of STAT5b-deficient mice for chemically induced colitis." (PMID 26938566, 2016). "STAT5B expression is reduced in the colon of Crohn’s disease patients and STAT5B deficient mice are more susceptible to colitis." (PMID 25927528, 2015). "In another study, using 2,4,6-trinitro-benzenesulfonic acid (TNBS)-induced colitis, it was shown that STAT5b is important for maintaining barrier integrity by increasing epithelial cell survival hence indicating that GH positively affects mucosal healing during intestinal inflammation." (PMID 28486400, 2017). "Similarly, chronic growth hormone administration is protective in experimental colitis through induction of STAT5b." (PMID 26938566, 2016).
lung carcinoma (5 papers, 2014 to 2025). "These analyses confirmed that the protective association of high STAT5B expression was particularly strong in hematologic malignancies (lnHR = −0.6988; 95% CI: −0.9780 to −0.4197; p < 0.0001) and lung cancers (lnHR = −0.5170; 95% CI: −0.8710 to −0.1630; p = 0.0042)." (PMID 41301421, 2025). "Similar trends were observed in lung cancer subtypes, where elevated STAT5B levels correlated with better outcomes across multiple independent cohorts." (PMID 41301421, 2025). "Subgroup analyses indicated that STAT5B was particularly protective in lung cancers (lnHR = −0.5170; p = 0.0042) and hematologic malignancies (lnHR = −0.6988; p < 0.0001)." (PMID 41301421, 2025). "In our study we assessed the immunoexpression of STAT5A and STAT5B proteins in lung cancer tissue and found it significantly higher than in normal lung tissue." (PMID 25137041, 2014). "In lung cancer and DLBCL, STAT5B expression could complement existing markers to refine risk stratification and guide treatment intensity." (PMID 41301421, 2025). "The obtained results highlight the importance of the genes STAT5B and COX-2 in lung cancer progression." (PMID 25137041, 2014). "Statistical analysis revealed that both STAT5A and STAT5B protein immunoexpression levels were significantly higher in lung cancer samples as compared with normal (macroscopically unchanged, control) lung tissues (P = 0.048 in case of STAT5A and P = 0.034 in case of STAT5B; U Mann-Whitney's test)." (PMID 25137041, 2014).
myeloid neoplasm (5 papers, 2019 to 2025). Proliferation of myeloid cells originating from a primitive stem cell. "We screened all 27 STAT5B N642H cases for mutations in other genes associated with myeloid neoplasms." (PMID 30573779, 2019). "Isolated reports have identified single cases of myeloid neoplasms, specifically chronic neutrophilic leukemia and MLN-eo, that tested positive for STAT5B N642H as well as 2 cases that developed clonal hematopoiesis following aplastic anaemia." (PMID 30573779, 2019).
neutropenia (5 papers, 2017 to 2022). A decrease in the number of neutrophils found in the blood. "In CD4+ T-LGLL, neutropenia is uncommon, and similarly, in our cohort STAT5B mutated patients had normal ANC levels but increased lymphocyte and LGL counts." (PMID 35210405, 2022). "Moreover, the 7 patients with STAT3 mutations have neutropenia and a CD56-/Vδ2- phenotype, and the 3 cases with STAT5B mutations display an asymptomatic clinical course and CD56/Vδ2 expression." (PMID 35676278, 2022). "In this study, we stratified 81 patients with RA and unexplained neutropenia or/and an increase in the number of LGLs into two groups (RA-associated T-LGLL or FS) based on the presence or absence of T-cell clonality; we then examined STAT3 and STAT5b gene mutations in both groups." (PMID 33280072, 2021).
T-cell neoplasms (5 papers, 2018 to 2023). "STAT5B N642H, described in other T-cell neoplasms, is located on the SH2 binding site, and is a gain-of-function mutation, likely explaining its association with ruxolitinib resistance." (PMID 37569479, 2023). "Transgenic mice harboring the STAT5B N642H lesion rapidly developed aggressive CD8+ T-cell neoplasms." (PMID 31766351, 2019). "Mutations of genes encoding for components of the JAK/STAT pathway are frequently found in T-cell neoplasms (predominantly mutations of JAK3, STAT3, and STAT5B)." (PMID 31766351, 2019). "Moreover, activating STAT5B mutations have been identified in a variety of hematological neoplasms, being identified as likely driver mutations in various T cell neoplasms, with JAK3 and STAT5B in the same mutation cluster in ALL." (PMID 35622134, 2022). "Indeed, the T-cell neoplasms induced by transgenic STAT5B N642H was markedly suppressed by JAK1/2 inhibition." (PMID 30573779, 2019). "While STAT5B-expressing mice lacked a hematopoietic phenotype, the STAT5BN642H-expressing mice rapidly developed T cell neoplasms." (PMID 29200404, 2018).
allergic disease (4 papers, 2017 to 2023). An immune response that occurs following re-exposure to an innocuous antigen, and that requires the presence of existing antibodies against that antigen. "Nearly half of the LD block of allergy variants (55 out of 93 SNPs) overlapped with the regulated actQTL peak and one of the variants, chr17:42,266,938 (rs34129849), also mapped to a 629-bp open chromatin region (chr17:42,266,595–42,267,224) located in intron one of the STAT5B gene." (PMID 35591976, 2022). "Moreover, it should be taken into account that these transcription factors, especially Stat5b, are directly involved in the correct expression of Foxp3, so that an alteration in their expression could also affect Foxp3 gene expression and, subsequently, susceptibility to allergic disease." (PMID 37334360, 2023).
asthma (4 papers, 2017 to 2025). "TR93 (stage IIA, squamous-cell carcinoma, 72-year-old male with asthma, heavy smoker) has the same STAT5B frame-shift mutation c.1102del as TR58." (PMID 38893104, 2024). "The association between asthma and the STAT5b isoform has been the most well studied relationship to date but a potential role for the STAT5a isoform is unclear." (PMID 28638418, 2017). "STAT5 consists of two isoforms, STAT5a and STAT5b, which can regulate lymphocyte proliferation, apoptosis, asthma and cancer." (PMID 36726128, 2023).
atopic dermatitis (4 papers, 2018 to 2024). "STAT5A SNP rs16967637 was also found to exacerbate the severity of atopic dermatitis in African Americans, whereas STAT5B SNP rs9900213 was found to increase the risk of atopic dermatitis in European Americans." (PMID 36232600, 2022).
colon carcinoma (4 papers, 2019 to 2023). "Case-control studies, using more than 1550 patients with colon cancer and 750 cases of rectal cancer, demonstrated that JAK2, SOCS2, STAT1, STAT3, STAT5A, STAT5B, and STAT6 were associated with colon cancer, and that STAT3, STAT4, STAT6, and TYK2 were linked to rectal cancer." (PMID 36982677, 2023).
COVID-19 (4 papers, 2022 to 2025). A disease caused by infection with severe acute respiratory syndrome coronavirus 2. "The kinase inhibitors dasatinib, nilotinib and imatinib which are associated with the predicted proteins CSFIR and STAT5B, are described as potential candidates for COVID-19 treatment." (PMID 40997149, 2025). "COVID-19 subsets additionally expressed LCP1, STAT5B, and ILF3, which are involved in T-cell activation and signaling." (PMID 36992700, 2023).
dermatitis (4 papers, 2018 to 2019). An inflammatory process affecting the skin. "It should also be noted that increased STAT5b activity, as observed in these patients, was associated with atopic-like skin inflammation that typically involves mast cell activation." (PMID 29755466, 2018). "Remarkably, the Foxp3YFP-Cre/YOgtfl/YRosa26Stat5b-CA/wt mice with STAT5B-CA overexpression specifically in OGT-deficient Treg cells alleviated skin inflammation, reduced sizes of the LNs and spleen, and prolonged lifespan, when compared to Foxp3YFP-Cre/YOgtfl/Y mice." (PMID 30664665, 2019).
enteropathy (4 papers, 2018 to 2021). "However, disease manifestations are not always consistent and clinical hallmarks of each disorder can be identified, such as enteropathy for IPEX, life-threatening infections in CD25 deficiency and severe growth failure for STAT5B deficiency." (PMID 34277517, 2021).
epilepsy (4 papers, 2019 to 2024). A brain disorder characterized by episodes of abnormally increased neuronal discharge resulting in transient episodes of sensory or motor neurological dysfunction, or psychic dysfunction. "It is known that STAT5B is a negative regulator of xCT expression, and HIF-1α is mediated by connexin 43 (Cx43), whose augmentation is linked to glioma-related epilepsy." (PMID 36295510, 2022). "However, on a protein level, we observed a significant decrease in protein expression of nuclear phosphorylated STAT5b in the epilepsy subgroup (Mann-Whitney U test, p = 0.004)." (PMID 30621209, 2019). "We performed qPCR experiments and immunohistochemistry on tissue microarrays containing 286 GBMs to further explore the association of these candidate pathways and of markers of mesenchymal transformation (NF-κB, CEBP-β, STAT3, STAT5b, VEGFA, SRF) with epilepsy." (PMID 30621209, 2019).
Laron syndrome (4 papers, 2010 to 2025). Laron syndrome is a congenital disorder characterized by marked short stature associated with normal or high serum growth hormone (GH) and low serum insulin-like growth factor-1 (IGF-I) levels which fail to rise after exogenous GH administration. "Similarly, mutations in STAT5B cause a Laron syndrome-like phenotype (OMIM 245590), but no hearing loss phenotype has been reported in Stat5b and Stat5a null mice (MGI:103035 and 103036)." (PMID 34680948, 2021).
liver cancer (4 papers, 2013 to 2019). An epithelial or non-epithelial malignant neoplasm that arises from the liver. "Suppression of hepatic STAT5b signaling is associated with lipid metabolic dysfunction leading to steatosis and liver cancer." (PMID 26959237, 2016). "Disruption of the GH hypothalamo-pituitary-liver axis controlling STAT5b activation can lead to metabolic dysregulation, steatosis, and liver cancer." (PMID 26959975, 2016). "In liver cancer cells, hypoxia-induced activation of STAT5B was shown to regulate expression of insulin-like growth factors, which are known to be involved in cell survival and differentiation." (PMID 23675504, 2013).
prolymphocytic leukemia (4 papers, 2016 to 2025). A mature B- or T- cell leukemia with progressive clinical course. "This case report presents a patient with T-prolymphocytic leukemia whose cytogenetic and molecular analysis revealed a t(X;14)(q28;q11.2) translocation and a STAT5B mutation." (PMID 40109866, 2025).
type 1 diabetes (4 papers, 2013 to 2025). "A recent review summarized the roles of STAT (STAT1, STAT3 and STAT5b) monogenic mutations in type 1 diabetes." (PMID 35242127, 2022). "We have reported that overexpression of Stat5b-CA in DCs reprograms the cells to acquire tolerogenic functions that induce and maintain protective immune response against type 1 diabetes in NOD mice." (PMID 32899608, 2020). "We have recently reported that NOD Stat5b transgenic mice have significantly lower incidence of type 1 diabetes than NOD mice and the levels of CD4+ regulatory T cells are increased in the Stat5b transgenic NOD mice." (PMID 23457589, 2013).
anemia (3 papers, 2016 to 2023). A reduction in the number of red blood cells, the amount of hemoglobin, and/or the volume of packed red blood cells. "Furthermore, just one-allele of either Stat5a or Stat5b is sufficient to prevent the perinatal lethality and anemia seen in STAT5-null mice, suggesting that molecular redundancy protects the most critical ‘life-and-death’ functions." (PMID 26999798, 2016). "Conversely, Stat5a−/− Stat5b−/− mice exhibited severe microcytic anemia." (PMID 37892192, 2023).
cervical cancer (3 papers, 2019 to 2024). A primary or metastatic malignant neoplasm involving the cervix. "Previous data from our group had shown that IL6R, JAK1/JAK2, and STAT3/STAT5b were dysregulated in locally advanced cervical cancer." (PMID 38891028, 2024). "STAT5B depletion also reduced cyclin D1 expression and increased p21 expression, confirming a role for STAT5 in HPV+ cervical cancer cell proliferation." (PMID 31817106, 2019).
colorectal cancer (3 papers, 2011 to 2022). A primary or metastatic malignant neoplasm that affects the colon or rectum. "The SAM programme typed the following genes to be statistically significant in the compared groups as genes differentiating stage I and II of clinical progression of colorectal cancer: AKT1, STAT3, MCL1, and STAT5B." (PMID 22363883, 2011).
growth hormone insensitivity syndrome (3 papers, 2018 to 2019). Growth hormone insensitivity syndrome (GHIS) is a group of diseases characterized by marked short stature associated with normal or elevated growth hormone (GH) concentrations, which fail to respond to exogenous GH administration. "STAT5B plays a key role downstream of the IL2 receptor and the growth hormone receptor (GHR), explaining why STAT5B defect causes Growth hormone insensitivity syndrome (GHIS) with a complex infectious and somatic phenotype." (PMID 30671054, 2018). "Clinical cases of patients with STAT5B LOF mutations on both alleles exhibit features similar to growth hormone insensitivity syndrome (GHIS)." (PMID 31717342, 2019).